FOXP2 (forkhead box P2)
Description:
Transcriptional repressor that may play a role in the specification and differentiation of lung epithelium. May also play a role in developing neural, gastrointestinal and cardiovascular tissues. Can act with CTBP1 to synergistically repress transcription but CTPBP1 is not essential. Plays a role in synapse formation by regulating SRPX2 levels. Involved in neural mechanisms mediating the development of speech and language.
Synonyms: CAGH44; TNRC10; SPCH1
Tractability: PROTAC: ubiquitination databases record sites on it.
Gene: Protein-coding gene on chromosome 7 (114,086,317 to 114,693,772, forward strand). Ensembl gene ENSG00000128573.
Subcellular location: Nucleus
Subcellular location (Human Protein Atlas): Nucleoplasm
Pathways (Reactome):
Cell-Cell communication: Positive Regulation of CDH1 Gene Transcription
Gene Ontology:
Molecular function: DNA binding; DNA-binding transcription factor activity; identical protein binding; protein binding; protein homodimerization activity; sequence-specific DNA binding; DNA-binding transcription factor activity, RNA polymerase II-specific; DNA-binding transcription repressor activity, RNA polymerase II-specific; RNA polymerase II cis-regulatory region sequence-specific DNA binding; transcription coregulator binding
Biological process: caudate nucleus development; cerebral cortex development; negative regulation of DNA-templated transcription; putamen development; regulation of transcription by RNA polymerase II; skeletal muscle tissue development; smooth muscle tissue development; vocalization behavior; animal organ development; cerebellar Purkinje cell differentiation; gene expression; negative regulation of transcription by RNA polymerase II; regulation of DNA-templated transcription; system development
Cellular component: nucleoplasm; nucleus; transcription regulator complex; chromatin
Genetic constraint (gnomAD): Loss-of-function variants: 11 observed, 115.82 expected, observed/expected ratio (o/e) 0.095, 90% interval 0.059 to 0.16. The upper end of that interval is the gene's LOEUF score, 0.16, which puts it in group 1 of 6, group 1 being the genes least tolerant of losing a copy. Missense variants: 628 observed, 881.47 expected, observed/expected ratio (o/e) 0.71, 90% interval 0.67 to 0.76. Synonymous variants: 328 observed, 311.34 expected, observed/expected ratio (o/e) 1.05, 90% interval 0.96 to 1.15.
Gene-disease validity (ClinGen):
ClinGen rates the evidence that FOXP2 causes each of these diseases.
specific language disorder (autosomal dominant): Definitive.
Homologues: Orthologues: chimpanzee FOXP2 (99% identical), macaque FOXP2 (99% identical), mouse Foxp2 (99% identical), guinea pig FOXP2 (99% identical), rat Foxp2 (99% identical), rabbit FOXP2 (99% identical), pig FOXP2 (98% identical), dog FOXP2 (95% identical), tropical clawed frog foxp2 (95% identical), zebrafish foxp2 (80% identical), Caenorhabditis elegans fkh-7 (27% identical). Paralogues in human: FOXP4 (58% identical), FOXF2 (13% identical), FOXI1 (11% identical).
Diseases named in the same sentence as FOXP2 in open-access papers:
FOXP2 is named in the same sentence as 141 diseases in open-access papers, as found by Europe PMC text mining. Sharing a sentence is not in itself a finding about the gene and the disease. The quoted sentences say what the papers report.
language disorder (92 papers, 2008 to 2025). A category of disorders characterized by an impairment in the development of an individual's language capabilities, which is in contrast to his/her non-verbal intellect. "Over two decades ago, a variant in FOXP2 was identified as the monogenic cause of a severe speech and language disorder in a large multigenerational family." (PMID 41236144, 2025). "Beyond speech and language disorders, we found enrichment of genes associated with other NDDs in the FOXP2+ cerebellar organoid population." (PMID 41236144, 2025). "FOXP2 was initially characterized as a transcription factor linked to speech and language disorders, but recent scRNAseq analyses have revealed that Foxp2 is also expressed in hormone-producing cells." (PMID 41410097, 2025). "The expression of FOXP2 in brain tissue is significantly elevated, indicating its association with genetic speech and language disorders, and its involvement in regulating motor function." (PMID 39588545, 2024). "FOXP2 is associated with speech and language disorders, ASD, and attention-deficit/hyperactivity disorder." (PMID 38010534, 2024). "Analysis of the genes targeted by these miRNAs highlights the Forkhead P2 box protein (FOXP2), which has been heavily implicated in speech and language disorders." (PMID 36735095, 2024). "In particular, FOXP2 seems important because its genetic abnormalities have been implicated in speech and language disorders." (PMID 37313401, 2023). "FOXP2 mutations can cause the ‘FOXP2-related speech and language disorder’ (FOXP2-SLD) with childhood apraxia of speech (CAS) as a core phenotype." (PMID 37860754, 2023). "The forkhead domain gene was found to be mutated in a severe speech and language disorder, and FOXP2 was found to be involved in the development of speech and language." (PMID 36138610, 2022). "Mutations in FOXP2 or the expression patterns of FOXP2 in the developing brain affect severe speech and language disorders." (PMID 36056347, 2022). "The FOXP2 gene, also known as the language gene, has been implicated in speech and language disorders based on imaging techniques and mice-mutated data." (PMID 36138610, 2022). "Single nucleotide polymorphisms in FOXP2 have been linked to speech- language disorder, autism, cancer and schizophrenia." (PMID 35944036, 2022). "A chromosomal inversion 200‐kb downstream of a well known language gene, FOXP2, causes a decrease in its expression, leading to language disorder in humans." (PMID 32722872, 2021). "FOXP2 is a transcription factor involved in the coordination of orofacial movements required for speech and whose alteration is associated with language disorders." (PMID 34445117, 2021). "FOXP2 was initially identified as the genetic factor of speech disorder, and its mutations lead to speech and language disorder." (PMID 31936744, 2020). "It was a series of studies of one extended pedigree which ultimately reported the first gene implicated in a speech and language disorder, FOXP2." (PMID 32635940, 2020). "Disruptions of the FOXP2 gene cause a speech and language disorder involving difficulties in sequencing orofacial movements." (PMID 30108312, 2019). "In humans, mutations in the transcription factor forkhead box P2 (FOXP2) result in language disorders associated with altered striatal structure." (PMID 31001575, 2019). "Functionally analogous, truncating FOXP2 mutations have been identified in some patients with speech and language disorders." (PMID 31099752, 2019). "The discovery that disruptions of one copy of the FOXP2 gene cause a severe speech and language disorder has generated substantial interest in elucidating the neural functions of the encoded protein." (PMID 30108312, 2019). "Mutations in FOXP2 cause a severe developmental speech and language disorder, known as childhood apraxia of speech." (PMID 31099752, 2019).
language disorder (continued). "FOXP2 was first implicated in the development of Language Disorder (LD), with haploinsufficiency linked to developmental verbal dyspraxia (DVD)." (PMID 31111659, 2019). "We found that the TBR1 variants abolished interactions with the FOXP1 and FOXP2 transcription factors involved in ID and severe speech/language disorder, respectively." (PMID 30250039, 2018). "Mutations in FoxP2 cause the only known monogenic language disorder in humans, and FoxP2 is involved in language and vocalization in multiple species." (PMID 29920554, 2018). "Mutations of the FOXP2 gene cause a severe speech and language disorder, providing a molecular window into the neurobiology of language." (PMID 29515369, 2018). "The neurexin family membrane protein CNTNAP2 is a target of FoxP2, and has been linked to language disorders as well as autism." (PMID 29920554, 2018). "Interesting evidence in line with our findings comes from the investigations of a hereditary language disorder in the KE family, due to a mutation in the FOXP2 gene, as mentioned in the previous section." (PMID 30618908, 2018). "Mutations in FoxP2 affect striatal circuitry both in human cases of speech/language disorder and in animal models of Foxp2 dysfunction." (PMID 30187194, 2018). "Heterozygous mutations of the FOXP2 gene cause a severe speech and language disorder characterized by childhood apraxia of speech (CAS) and accompanied by expressive and receptive language problems." (PMID 29515369, 2018). "FOXP2, the first single gene linked to a speech and language disorder, is important for the correct execution of complex motor behaviors used for speech." (PMID 30187194, 2018). "The gene coding for the forkhead box protein P2 (FOXP2) is associated with human language disorders." (PMID 29203828, 2017). "For example, the FOXP2 mutation that causes a severe speech and language disorder in the KE family is a change to a single letter of DNA, leading to alteration of the amino-acid sequence of the encoded protein." (PMID 27432000, 2017). "FOXP2 is the first gene that was discovered to be associated with language disorders and fine orofacial motor control, as two functional copies are required for normal development of speech and language in humans." (PMID 29203828, 2017). "For example, some genes that are regulated by FOXP2, a transcription factor involved in a familial speech-language disorder, have been implicated in language deficits." (PMID 28400738, 2017). "Heterozygous disruptions of the FOXP2 gene cause a rare and severe speech and language disorder (OMIM 602081)." (PMID 27933109, 2016). "FOXP2 is the major gene associated with severe, persistent, developmental speech and language disorders." (PMID 27734906, 2016). "Our experiments provide a framework for the characterization of novel FOXP2 variants uncovered through future genetic analyses of individuals with speech/language disorder." (PMID 27933109, 2016). "An aetiological FOXP2 mutation found in a family with speech and language disorder markedly reduced FOXP2 SUMOylation." (PMID 26867680, 2016). "In a similar fashion, FOXP2 was the first gene implicated in developmental speech and language disorders, and missense mutations of FOXP2 result in verbal apraxia, a hallmark of ASD." (PMID 27105825, 2016). "Our findings highlight the importance of functional characterization of novel rare variants in FOXP2 in assessing the contribution of such variants to speech/language disorder and provide further insights into the molecular function of the FOXP2 protein." (PMID 27933109, 2016). "Mutations affecting the transcription factor FOXP2 cause a rare form of severe speech and language disorder." (PMID 26867680, 2016). "The second mouse model mirrors an early stop codon in exon 7 introduced by a non-sense mutation that leads to a loss of FOXP2 protein in an independent family with speech/language disorder." (PMID 26635706, 2015).
language disorder (continued). "Of these transcription factors, FOXP2 is of particular interest, because its genetic abnormalities have been implicated in speech and language disorders." (PMID 26010484, 2015). "Mutations of the forkhead transcription factor FOXP2 gene have been implicated in inherited speech-and-language disorders, and specific Foxp2 expression patterns in neuronal populations and neuronal phenotypes arising from Foxp2 disruption have been described." (PMID 26034982, 2015). "A breakthrough in speech and language genetics came with the identification of the first gene to cause a speech/language disorder: FOXP2." (PMID 26635706, 2015). "Initially, a heterozygous point mutation in FOXP2 was famously identified as being associated with a language disorder, developmental verbal dyspraxia, in a British family." (PMID 26284006, 2015). "FOXP2 was considered the most promising candidate gene, given that haploinsufficency of this gene is known to cause speech and language disorders with a similar phenotype." (PMID 26300977, 2015). "Mutations in the FOXP2 gene are known to cause rare forms of speech and language disorder, the first report of which was the KE family in 2001." (PMID 25309332, 2014). "The homologous gene RBFOX1 has been implicated in several neurodevelopmental disorders, including Rolandic Epilepsy and Autism Spectrum Disorder, and is a downstream target of FOXP2, a transcription factor implicated in monogenic speech and language disorders." (PMID 25065397, 2014). "The striatum represents a site of pathology both structurally and in measures of functional activation during language related processing tasks in speech/language disorder patients carrying FOXP2 mutations." (PMID 25309332, 2014). "The most thoroughly studied FOXP2 disruption is a heterozygous missense mutation that co-segregates with speech and language disorder in 15 members of a three generation pedigree, known as the KE family." (PMID 25013396, 2014). "The FOXP2 transcription factor is one of the most well-known genes to have been implicated in developmental speech and language disorders." (PMID 25013396, 2014). "The forkhead box P2 gene, designated FOXP2, is the first gene implicated in a speech and language disorder." (PMID 24765219, 2013). "Heterozygous mutations of the human FOXP2 transcription factor gene cause the best-described examples of monogenic speech and language disorders." (PMID 22412993, 2012). "We studied these aspects of learning in mice carrying heterozygous Foxp2 mutations that are similar to those implicated in human speech and language disorders." (PMID 22412993, 2012). "Foxp2(R552H) knock-in (KI) mouse pups with a mutation related to human speech–language disorders exhibit poor development of cerebellar Purkinje cells and impaired ultrasonic vocalization (USV), a communication tool for mother-offspring interactions." (PMID 22272290, 2012). "Heterozygous mutations of human FOXP2 cause severe speech and language disorders involving deficits in rapid coordinated orofacial movements and impaired expression and reception of language." (PMID 20132318, 2010). "Heterozygous mutations of the human FOXP2 gene are implicated in a severe speech and language disorder." (PMID 20132318, 2010). "It is likely that in the future, the investigation of the pathways that involve and intersect with FOXP2 will identify many more candidate genes and mechanisms underlying speech and language disorders." (PMID 20955937, 2010). "Mutations in FoxP2 have also been implicated in both language disorders and autism, the latter of which is characterized by both language and amygdala-based impairments." (PMID 20507551, 2010). "The most well-described example of an inherited speech and language disorder is that observed in the multigenerational KE family, caused by a heterozygous missense mutation in the FOXP2 gene." (PMID 18328704, 2008).
language disorder (continued). "Moreover, the molecular evolution of FOXP2 identified from the KE family associated with language disorders is important for human signatures." (PMID 38010534, 2024). "Recently, some roles of FOXP2 have been verified in cancer development as a tumor suppressor, though its mutations could cause language disorders." (PMID 35614183, 2022). "Indeed, mutations in the FOXP2 gene have been identified in patients with a severe speech and language disorders." (PMID 36081908, 2022). "It has been shown to impact gene regulation in multiple aspects of neuronal development.Indeed, Forkhead-box protein P2 (FOXP2) was one of the first genes to be linked to human language disorder, characterized by a broader cognitive dysfunction and primary motor impairment." (PMID 34428113, 2021). "Twenty years ago, FOXP2 became the first gene implicated in a speech and language disorder." (PMID 34773992, 2021). "In humans, FOXP2 has been most closely linked to language disorders." (PMID 34421555, 2021). "By contrast, when mice were genetically modified to carry a disruptive FOXP2 mutation that is known to cause a speech and language disorder (the mutation from the KE family) such mice showed lower levels of synaptic plasticity in cortico-basal ganglia circuits, consistent with a loss of function." (PMID 27432000, 2017). "Variants affecting the dimerization of FOXP2 might therefore be a cause of speech/language disorder." (PMID 27933109, 2016). "A further mechanism by which variants in FOXP2 might lead to speech/language disorder is through disruption of protein-protein interactions between FOXP2 and crucial mediators of transcriptional regulation." (PMID 27933109, 2016). "A point mutation disrupting the DNA-binding domain of FOXP2 was seen to segregate with a severe speech and language disorder in the multi-generational KE family, and screening of unrelated individuals with similar problems identified additional subjects harboring FOXP2 mutations." (PMID 27351196, 2016). "In conjunction with previous research indicating the rare and specific nature of FOXP2 mutations in the etiology of speech and language disorders, these findings lead us to conclude that common variants are unlikely to exert a large effect in typical language development." (PMID 27064276, 2016). "However, it will be necessary to identify further cases of FOXP2-related speech/language disorder resulting from missense variants in order to assess differences in phenotypic outcome." (PMID 27933109, 2016). "For example, the R553H mutation in FOXP2 (equivalent to FOXM1 R286) is associated with development of a severe speech language disorder, while a mutation of the same arginine residue in FOXC2 (R121C) is associated with a developmental disorder affecting the lymphatic vasculature system." (PMID 26100407, 2015). "FOXP2 was the first single gene identified to cause speech and language disorder." (PMID 26635706, 2015). "FOXP2 was the first gene shown to cause a Mendelian form of speech and language disorder." (PMID 25309332, 2014). "Mutations in human foxP2 gene lead to severe language disorders." (PMID 24987514, 2014). "Mutations of FOXP2 have been linked to speech and language disorders and ASD." (PMID 23815876, 2013). "A previous study found an R553H mutation in human FOXP2 in patients with speech–language disorders." (PMID 22272290, 2012). "Heterozygous mutations of the human FOXP2 gene cause a monogenic speech and language disorder." (PMID 21765815, 2011). "Mutations in the FOXP2 transcription factor lead to language disorders with developmental onset." (PMID 20062527, 2010). "In addition to speech and language disorders, FOXP2 has also been implicated it in adult ADHD42,43." (PMID 33658499, 2021). "Finally, whether specific RNA splicing events, e.g. of the FOXP2 gene, a gene implicated in speech and language disorders, may contribute to this dyslexic features remain presently open." (PMID 32851461, 2021).